NPIPA7 (nuclear pore complex interacting protein family member A7)
Synonyms: NPIPA8
Tractability: No criterion of Open Targets' tractability assessment is met for any kind of drug.
Gene: Protein-coding gene on chromosome 16 (16,371,207 to 16,393,972, forward strand). Ensembl gene ENSG00000214967.
Subcellular location (Human Protein Atlas): Nucleoplasm
Gene Ontology:
Molecular function: protein binding
Homologues: Paralogues in human: NPIPA8 (100% identical), NPIPA6 (99% identical), NPIPA9 (99% identical), NPIPA1 (93% identical), NPIPA5 (93% identical), NPIPA2 (88% identical), NPIPA3 (88% identical), NPIPB2 (72% identical), NPIPB12 (70% identical), NPIPB13 (70% identical), NPIPB4 (70% identical), NPIPB5 (70% identical), and 7 more.